TRPV1 (transient receptor potential cation channel subfamily V member 1)
Diseases named in the same sentence as TRPV1 in open-access papers (continued):
Sharing a sentence is not in itself a finding about the gene and the disease.
cancer (continued). "Several studies have shown that calcium‐regulating factors such as TRPV1, SERCA, ORAI, and STIM affect cancer metastasis and growth." (PMID 34743414, 2022). "It would be also interesting to synthesize and develop pharmacological compounds that target TRPV1, TRPV2, and TRPA1 that were shown to be downregulated in some types of cancers and whose activity enhances differentiation and impairs stemness." (PMID 36142596, 2022). "TRPV1 in KIRC, TRPV2 in LUSC, TRPV3 in BRCA, TRPV6 in LUAD and BRCA, while TRPV4 in KIRC and BRCA differed significantly across different cancer subtypes (P <0.05)." (PMID 35174089, 2022). "In this study, we discovered that TRPV1 expression is significantly upregulated in NSCLC, thus providing further evidence that altered TRPV1 expression in cancer is tumor-type specific." (PMID 35402237, 2022). "Survival analyses showed a positive correlation between TRPV1 expression and survival prognosis (OS, DSS, and PFI) in pan-cancer (log-rank test, p < 0.001)." (PMID 36304985, 2022). "As fibroblasts act as important mediators for other TME components 132, 133, it would be interesting to further investigate the relationship between TRPV1 and TGF-β in cancer cells and cancer-related fibroblasts." (PMID 34131404, 2021). "TRPV1 and TRPV2 are the best-studied receptors of this family that appear to be up-regulated in several cancers." (PMID 31979368, 2020). "Thus, slight potentiation of TRPV1-dependent contractility of isolated DSM strips from cancerous bladder would be indicative of enhanced “efferent” function of TRPV1-expressing bladder afferents due to release of pro-contractile tachykinins in response to TRPV1 activation." (PMID 33184390, 2020). "We therefore examined the mRNA expression of seven cannabimimetic receptors – CNR1 (CB1), CNR2 (CB2), GPR55, TRPV1, TRPV2, TRPA1, TRPM8 – and found them to be differentially expressed amongst the 12 tested cancer cell lines." (PMID 31289609, 2019). "Oxidation of thiol redox system and cysteine groups in cancer cells have the main role in the activation of thiol group containing TRP channels such as TRPA1, TRPM8 and TRPV1." (PMID 30858386, 2019). "Regarding agonists or antagonists of TRPM8 channels, several are now considered in cancer prevention and therapy, although some of those reported in the literature lack selectivity for TRPM8 because they also act on TRPV1 and TRPA1." (PMID 31801263, 2019). "TRPV1, TRPC1, TRPC6, and TRPM5 are also increased in cancer tissues, but further experiments are required to study the underlying mechanisms." (PMID 27023518, 2016). "Our data suggest that IB4(+) and TRPV1(+) neurons have functionally distinct roles in cancer pain, at least in the level of mouse DRG and spinal cord, where few IB4(+) neurons overlap with TRPV1, in contrast to rat DRG." (PMID 24524628, 2014). "Chronic exposure to CAP, however, may result in downregulation and internalization of ESR1, as well as TRPV1 stimulation of glucagon-like peptide 1 (GLP-1) expression, both of which downregulate GLUT expression, thereby starving cancer cells of glucose." (PMID 40003617, 2025). "The TRPV1, TRPV2, and TRPV4 receptors play a significant role in cancer pathology." (PMID 40006844, 2025). "Although our cancer models are non-neural, they reiterate that the hypoxia–Ca2+–mitochondria axis is context-sensitive and that TRPV1-driven Ca2+ influx can amplify this variability." (PMID 41303593, 2025). "Although some studies suggest that CBC might modulate inflammation and neurological functions through ECS receptors, such as TRPV1 and CB2, a significant gap in the understanding of its direct anti-cancer mechanisms remains." (PMID 40790027, 2025).
cancer (continued). "These suggest that TRPV1 may regulate transforming growth factor TGF-β, modulating CAF, and thus be involved in cancer development." (PMID 40007993, 2025). "Capsaicin, a well-studied nutraceutical compound, and its selective TRPV1 antagonist AMG9810, extensively used in preclinical models of pain, inflammation, and cancer, were both effective in modulating TRPV1 activity in OS cells while sparing healthy hFOB osteoblasts." (PMID 41009392, 2025). "Our experiments using Annexin V/PI staining and FACS analysis revealed that CBC-induced cell death was significantly affected when CB2 and TRPV1 were silenced using siRNA, indicating that CBC might exert its anti-cancer effects through these two receptors." (PMID 40790027, 2025). "The injection of purified cancer-derived vesicles into naïve mice induces hypersensitivity that was absent in TRPV1-null animals." (PMID 38339399, 2024). "While it exhibits anticancer effects through TRPV1 modulation and Ca2+ signaling interference, its impact on different cancer types of cells is not fully explored." (PMID 39273976, 2024). "TRPV1 can regulate CD4+ T cell activation and pro-inflammatory properties, suggesting that its modulation could enhance the immune response against cancer." (PMID 39407657, 2024). "Furthermore, the modulation of TRPV1 influences calcium influx, impacting signaling pathways like PI3K/Akt and MAPK, which are dysregulated in cancer." (PMID 39407657, 2024). "A key mechanism is the activation of TRPV1, a non-selective calcium channel, which plays a pivotal role in capsaicin-induced apoptosis across multiple cancer types." (PMID 39407657, 2024). "This unbiased assay identified after a 24-h exposure, novel sensitizers, including cancer chemotherapeutic agents and proteasome inhibitors, a class of compounds not previously reported to activate or sensitize TRPV1." (PMID 38052846, 2023). "In this work, we show that nanoparticle-mediated TRPV1 blockade selectively suppresses stressful HSP70 and TGFβ1 via effective modulation of heat shock factor 1 (HSF1) for augmented thermo-immunotherapy against highly malignant tumors." (PMID 37120615, 2023). "On the other hand, as cited before, capsaicin appears to induce changes in anion secretions and induction of apoptosis of cancer cells by mechanisms independent of TRPV1." (PMID 37892544, 2023). "The mechanism by which capsaicin induces apoptosis in cancer cells is not well understood, but it appears to be independent of the TRPV1 receptor as neither capsazepine, a TRPV1 antagonist, nor intracellular Ca2+ chelators have been found to inhibit apoptosis." (PMID 37612326, 2023). "Our results that the SN TRPV1 contributes to BC progression and metastasis, as well as BCIBP induction, may provide a molecular basis for the poor outcome in cancer patients with pain." (PMID 37461623, 2023). "In 366 patients’ cases and the Cancer Cell Line Encyclopedia from Novartis and Broad Institute, which were analysed for mutations in CNR1, TRPV1 and PPARα, up to 3% were mutated (with no mutational hotspot)." (PMID 37237519, 2023). "Our analysis revealed significant negative correlations between TRPV1 expression levels and the enrichment scores of numerous immunosuppressive signatures in pan-cancer and in most cancer types (p < 0.05)." (PMID 36304985, 2022). "Several studies merely showed that TRPV1 ligands had anti-cancer effect independent of TRPV1 in NSCLC." (PMID 35402237, 2022). "Our analysis supports a significant negative correlation between TRPV1 expression and tumor progression in pan-cancer and multiple individual cancer types." (PMID 36304985, 2022).
cancer (continued). "The nonselective cation channel TRPV1 (transient receptor potential cation channel subfamily V member 1) plays significant roles in cancer onset and advancement." (PMID 36304985, 2022). "It is in line with previous studies showing that TRPV1 expression correlates negatively with the expression of cancer proliferation and metastasis-related markers (Ki67 and VEGFR) and that the activation of TRPV1 can significantly inhibit cancer cell growth by inducing apoptosis and necrosis." (PMID 36304985, 2022). "We found significant negative correlations between TRPV1 expression levels and tumor stemness scores in pan-cancer (p = 1.47 × 10−77; ρ = −0.26) and in eight cancer types (p < 0.01)." (PMID 36304985, 2022). "Hypoxic TRPV1 modulation is reported in several publications, although cancer-related studies are lacking." (PMID 35806388, 2022). "For the first time, we comprehensively analyzed the correlations of TRPV1 expression levels with tumor proliferation, stemness, EMT, genomic instability, ITH, immunity, and various clinical features in pan-cancer and diverse cancer types." (PMID 36304985, 2022). "Also, in five individual cancer types (BLCA, HNSC, LIHC, PAAD, and SKCM), TRPV1 downregulation correlated with worse OS (p < 0.05)." (PMID 36304985, 2022). "Unlike its effect on migration, the effect of TRPV1 on cancer cell invasion has been relatively well characterized and studied, and TRPV1 is believed to function as an invasion repressor." (PMID 34131404, 2021). "NF-kB and STAT3 are known to be regulators of VEGF in several cancers 161-163 and may be involved in the regulation of VEGF expression by TRPV1." (PMID 34131404, 2021). "The expression of TRP channels, such as transient receptor potential vanilloid 1 (TRPV1) and transient receptor potential ankyrin 1 (TRPA1), in cells involved in detecting cancer pain and their role in pain-sensing makes them potential targets for pain relief compounds." (PMID 35053150, 2021). "Exogenous and endogenous TRPV1 agonists, applied in conjunction with P2Y2 and EGFR antagonists, may therefore constitute a potential form of anti-cancer therapy." (PMID 32545311, 2020). "CKI can also block TRPV1 signaling by inhibiting TRPV1-mediated capsaicin-induced ERK phosphorylation and reducing tumor-induced proinflammatory cytokine production, indirectly limiting cancer pain by reducing tumor growth." (PMID 32020871, 2020). "Moreover, the expression of TRPV1 was closely correlated with Ki67, VEGFR, and E-cadherin, all of which are the well-known cancer markers for proliferation and metastasis." (PMID 33008449, 2020). "TRPV1 has been identified in several organelles, such as the ER, sarcoplasmic reticulum, mitochondria, Golgi complex, and lysosomes of several cell types, including HEK 293, HeLa, DRG, skeletal myocyte, and microglia, as well as several cancer cells." (PMID 31547874, 2019). "The role of TRPV1 and TRPV4 in transducing cancer-induced hyperalgesia is investigated." (PMID 29637027, 2018). "We studied the possible role of TRPV1 and TRPV4 in transducing cancer-induced hyperalgesia." (PMID 29637027, 2018). "Even an intrathecally administered 1 μg/kg dose of RTX can rapidly eradicate the inflammatory pain signaling by a robust TRPV1-amplified cytotoxicity without significant side effect, tested in patient dogs suffering either cancer or osteoporosis pain." (PMID 28626428, 2017). "A growing body of evidence implicates members of the TRP family, including TRPV1, TRPV2, and TRPM8, in calcium-mediated signal transduction that regulates proliferation, migration, and metastasis of cancer cells (reviewed by Déliot and Constantin, 2015; Yee, 2015)." (PMID 29066974, 2017). "The relative mRNA levels of c-fos and TRPV1 in the ipsilateral spinal cord and of ASIC3 in the ipsilateral DRG in the cancer, cancer with NS, cancer with ZOL and cancer with TA groups were significantly increased, compared with the naive and sham groups (P<0.05)." (PMID 26081451, 2015).
cancer (continued). "The mRNA expression of TRPV1 in the spinal cord was not significantly different among the cancer groups." (PMID 26081451, 2015). "Several reports implicate TRPV1 and TRPA1 in cancer pain, although there is a large gap in knowledge since the mechanisms for tumor-induced activation of these TRP receptors are unknown." (PMID 26007300, 2015). "In addition to SOCE channels, several TRP channels contribute to the migration of cancer cells, including TRP channels TRPC1, TRPM7, TRPM8, TRPV1, TRPV2, and TRPV6." (PMID 26496025, 2015). "Our study demonstrated distinct roles of nonpeptidergic IB4(+) and peptidergic TRPV1(+) neurons in mediating cancer-induced nociception." (PMID 24524628, 2014). "In particular, a modulation of TRPV1 activity could be interestingly investigated in the management of NMIBC after a transurethral resection for both the anti-inflammatory and cancer recurrence rate decreasing possible features." (PMID 24901005, 2014). "The differential involvement of IB4(+) and TRPV1(+) neurons in cancer pain has not been well-characterized." (PMID 24524628, 2014). "We determined that TRPV1(+) neurons are involved exclusively in cancer-induced thermal hyperalgesia, but not mechanical allodynia in our mouse paw SCC model." (PMID 24524628, 2014). "By Western blotting, the expression of TRPV1 was the lowest in high grade carcinoma in comparison to normal urothelium and to low grade carcinoma." (PMID 24868547, 2014). "LPA (0.01 μM) could potentiate the TRPV1 current induced by 0.05 μM capsaicin in 31.58% (n = 19) DRG neurons of sham rats and 60% (n = 19) cells in cancer rats." (PMID 21118579, 2010). "TRPV1 may regulate TGF-β/CAF and influence cancer development." (PMID 40007993, 2025). "Studies have shown that in TRPV1-/- mice, the NF-kB and STAT3 signaling pathways are overactivated, leading to a group of inflammatory factors (including IL-1 and IL-6) as well as invasive factors (such as MMP9 upregulation) that contribute to the development of cancer." (PMID 40007993, 2025). "Similarly, TRPV1 and TRPA1, although originally characterized for their roles in pain perception and inflammation, were increasingly recognized for their involvement in cancer cell adaptation to mechanical and oxidative stress." (PMID 41009392, 2025). "Furthermore, a multitarget cross‐activity may be beneficial in cancer patients treated with chemotherapy that develop a distal peripheral neuropathy, where a contribution of TRPM8, TRPV1, and TRPA1 channels has been reported." (PMID 40123199, 2025). "In addition, TRPV1-/- mice did not exhibit pain behaviors in response to cancer sEVs administration, and the ablation of TRPV1-positive neurons with resiniferatoxin prevented the development of both evoked and spontaneous pain in a murine model of HNSCC." (PMID 39811726, 2024). "Finally, TRPV4 is co-expressed with different TRP channels (TRPV1 and TRPA1), and the blockage of these receptors may also reduce cancer-induced nociception." (PMID 38730655, 2024). "Interestingly, cancers display higher electrical activity than normal tissues, and tumors implanted into transgenic mice lacking TRPV1-positive nociceptors neurons show reduced electrical activity." (PMID 38339399, 2024). "Most important, it is not clear whether or not sensory denervation mediated by TRPV1 agonists affects cancer progression." (PMID 38339399, 2024). "Although these studies did not directly measure the density of TRPV1-positive sensory neurons in cancer tissues, it can be argued that changes in intra-tumoral TRPV1 predominantly reflects changes in TRPV1-positive nerve fibers within the tumor microenvironment." (PMID 37371563, 2023). "Second, this research used the mRNA expression data to perform all analyses, which may not fully recapitulate the protein expression profiles of TRPV1 in cancer." (PMID 36304985, 2022).
cancer (continued). "Moreover, TRPV1 expression correlated negatively with the expression of RACGAP1, another marker for cell proliferation, in pan-cancer (p = 5.80 × 10−98; r = −0.29) as well as in five cancer types (p < 0.001)." (PMID 36304985, 2022). "From our demonstration that back labeled tongue afferent fibers co-express PAR2 and TRPV1, along with our demonstration that PAR2 activation enhances the calcium influx induced by TRPV1, we infer that PAR2 and TRPV1 on sensory neurons mediate the capsaicin sensitivity observed in our cancer model." (PMID 35260737, 2022). "Polygodial, its epimer 49 and warburganal were found to be agonists of the non-selective ion channel TRPV1 (transient receptor potential vanilloid 1), which is expressed on the cell surface of several cancer cell lines as well as on the mitochondrial membrane of different human cells." (PMID 35458699, 2022). "In fact, both agonists and antagonists may reveal anti-cancer effects, and the effect may function via or be independent of TRPV1." (PMID 35214061, 2022). "The PLC, PI3K, and MAPK-ERK signaling pathways, activate downstream kinases, such as PKC and PKA, which phosphorylate TRPV1 and TRPA1 channels and promote channel sensitization and reduction of their activation threshold, potentially contributing to the pain sensation experienced by cancer patients." (PMID 35053150, 2021). "Our finding that pharmacologic ablation of IB4(+) and TRPV1(+) subtypes did not lead to a decrease in proliferation could be due to compensatory sprouting of autonomic or sensory neurons which maintains cancer proliferation." (PMID 24524628, 2014). "By immunofluorescence, all samples of high grade carcinoma were TRPV1 negative." (PMID 24868547, 2014). "Our data suggest that application of neuroleptics in severe cancer pain may enhance and complement efficacy of conventional painkillers by direct inhibition of TRPV1 Ca2+-channel, an alternative target not used by opiates and NSAIDs." (PMID 17579717, 2007). "However, it is not known how TRPV1 expression in NK and dendritic cells may change in cancer patients." (PMID 37371563, 2023). "The activity of TRPV1 could increase when the expression had no change and involved in cancer pain." (PMID 36438444, 2022). "It is still unknown whether TRPV1 or TRPM8 is involved in controlling germline mutations of epigenetic modifiers in RB, yet Ca2+ signaling from nociceptive TRP channels may influence epigenetic mechanisms in determining non-aging-associated cancer development." (PMID 36045706, 2021). "However, both agonists and antagonists may reveal anti-cancer effects, and the effect may function via or be independent of TRPV1." (PMID 34131404, 2021). "However, in most cases, this action on cancer cells’ metabolism seems to be independent of TRPV1." (PMID 33379302, 2020). "Therefore, we believe that a possible strategy to treat various cancers could utilize substances known to regulate the HSR through a membrane receptor capable of reducing the expression of heat shock proteins such as Capsazepine or AMG-132 and TRPV1 siRNA." (PMID 27200359, 2016). "Chronic administration of the TRPV1 antagonist JNJ-17203212 or disruption of the TRPV1 gene significantly attenuated, but not abolished, cancer-induced ongoing and movement-evoked nocifensive behaviors in mice." (PMID 38791867, 2024). "Thus, our findings indicate a link among cisplatin resistance, EGFR hyperactivation, and TRPV1-mediated autophagic secretion, and implicate that TRPV1 could be a crucial drug target that could not only overcome cisplatin resistance but also alleviate pain in NANOG+ cisplatin-resistant cancer." (PMID 37165076, 2023). "Our analysis revealed a significant negative correlation between TRPV1 expression levels and ITH scores in pan-cancer (p = 9.61 × 10−8; ρ = −0.081)." (PMID 36304985, 2022). "TRPV1 had a negative relationship with the well-recognized cancer suppressor gene Pten and a positive relation with VEGFA, a known cancer promoting gene." (PMID 32913462, 2020).